ABRACL (ABRA C-terminal like)
Description:
Associates with the actin cytoskeleton and may modulate actin dynamics, in favor of increasing the relative content of F-actin, therefore may play a role in cell migration. May be acting by inhibiting CFL1-mediated actin depolymerization.
Synonyms: C6orf115; HSPC280; PRO2013; Costars
Tractability: PROTAC: ubiquitination databases record sites on it; its protein half-life has been measured.
Gene: Protein-coding gene on chromosome 6 (139,027,494 to 139,043,742, forward strand). Ensembl gene ENSG00000146386.
Subcellular location: Cell projection, lamellipodium; Cell projection, cilium
Subcellular location (Human Protein Atlas): Nucleoplasm; Cytosol
Gene Ontology:
Biological process: regulation of actin filament-based process
Cellular component: cilium; lamellipodium
Genetic constraint (gnomAD): Loss-of-function variants: 4 observed, 7.34 expected, observed/expected ratio (o/e) 0.55, 90% interval 0.27 to 1.24. That is too few expected variants to judge how well the gene tolerates losing a copy. Missense variants: 104 observed, 101.46 expected, observed/expected ratio (o/e) 1.02, 90% interval 0.87 to 1.21. Synonymous variants: 30 observed, 37.92 expected, observed/expected ratio (o/e) 0.79, 90% interval 0.59 to 1.07.
Homologues: Orthologues: chimpanzee ABRACL (100% identical), dog ABRACL (99% identical), guinea pig ABRACL (98% identical), macaque ABRACL (98% identical), pig ABRACL (94% identical), rabbit ABRACL (94% identical), rat Abracl (94% identical), mouse Abracl (93% identical), zebrafish abracl (80% identical).
Diseases named in the same sentence as ABRACL in open-access papers:
ABRACL is named in the same sentence as 9 diseases in open-access papers, as found by Europe PMC text mining. Sharing a sentence is not in itself a finding about the gene and the disease. The quoted sentences say what the papers report.
breast carcinoma (2 papers, 2022 to 2025). "In the present study, the expression of ABRACL in breast cancer tissues and overall survival were analyzed by using GEPIA2 database." (PMID 35341461, 2022). "Meanwhile, this study highlights that ABRACL acts as a novel molecular player in breast cancer pathogenesis." (PMID 35341461, 2022). "The high expression of ABRACL contributed to a significantly decreased overall survival of breast cancer patients (Logrank P = 0.024)." (PMID 35341461, 2022). "Overall, these findings highlight the inhibitory effects of ABRACL knockdown on breast cancer cell proliferation." (PMID 35341461, 2022). "To conclude, ABRACL could be transcriptionally regulated by MYBL2 to promote cell malignant biological behaviors in breast cancer cells, implying the potential of ABRACL being a promising target for the improvement of breast cancer therapy." (PMID 35341461, 2022). "For the sake of figuring out whether ABRACL had an effect on the proliferative ability of breast cancer cells, we first knocked down ABRACL expression in MCF-7 cells." (PMID 35341461, 2022). "The evidences showed in this section note that MYBL2 overexpression reverses the regulatory effects of ABRACL knockdown on the relative invasion and migration rate, as well as EMT process of breast cancer cells." (PMID 35341461, 2022). "Obviously, ABRACL knockdown appears to inhibit the relative invasion and migration rate as well as EMT in breast cancer cells." (PMID 35341461, 2022). "With the application of RT-qPCR and western blot, the mRNA and protein expression of ABRACL and MYBL2 in breast cancer cell lines were assessed." (PMID 35341461, 2022). "In this study, biological information analysis predicted the expression of ABRACL and MYB proto-oncogene-like 2 (MYBL2) in breast cancer tissues and their possible relationship." (PMID 35341461, 2022). "Previous findings confirmed that ABRACL knockdown could inhibit the malignant behaviors and EMT of breast cancer cells and was transcriptionally regulated by MYBL2." (PMID 35341461, 2022). "Results revealed that ABRACL and MYBL2 were highly expressed in breast cancer tissues and cells." (PMID 35341461, 2022). "Given that the expression of ABRACL and MYBL2 was upregulated in breast cancer cells, the following experiments were conducted to verify whether there was a link between them." (PMID 35341461, 2022). "ABRACL knockdown suppressed the proliferation, invasion, migration, and EMT of breast cancer cells." (PMID 35341461, 2022). "In view of all that has been discussed so far, we can conclude that ABRACL can be transcriptionally regulated by MYBL2 to promote the proliferative ability, relative migration rate, invasive ability, as well as EMT process of breast cancer cells." (PMID 35341461, 2022). "Furthermore, MYBL2 overexpression also upregulated the content of ABRACL, suggesting that the high expression of ABRACL might contribute to the malignant biological behaviors and EMT process of breast cancer cells as well." (PMID 35341461, 2022). "For the seven stemness model genes identified in this study, ABRACL has been proposed as a prospective biomarker in endometrial cancer uterine aspirate, and Li and Chen reported that ABRACL deletion could suppress proliferation, invasion, migration, and EMT of breast cancer cells." (PMID 40182754, 2025).
endometrial cancer (2 papers, 2017 to 2025). Primary or metastatic malignant neoplasm involving the endometrium (mucous membrane that lines the endometrial cavity). "In this study, western blot (WB) analysis from ten endometrial cancer vs six normal endometrium was used to validate the abundance of the four proteins which discriminate unambiguously between cases and controls (ABRACL, PGAM2, FGB, ANXA3)." (PMID 29312627, 2017). "From the discovery phase, four proteins (costars family protein ABRACL, phosphoglycerate mutase 2, fibrinogen beta chain, annexin A3) were found to be present in the uterine aspirate of endometrial cancers and not in healthy aspirates." (PMID 29312627, 2017).
colon cancer (1 paper, 2021). "Lastly, analysis on a colorectal cancer cohort demonstrated that high ABRACL expression was associated with distant metastasis, and further exploration showed that depletion of ABRACL expression in colon cancer cells resulted in reduced cell proliferation and tumorigenic growth." (PMID 33670794, 2021). "Immunohistochemistry (IHC) analysis on human colon cancer tissue sections showed strong ABRACL immunoreactivity in the tumor but not in adjacent non-tumor tissues." (PMID 33670794, 2021).
colorectal cancer (1 paper, 2021). A primary or metastatic malignant neoplasm that affects the colon or rectum. "Furthermore, analyses revealed the upregulation of ABRACL expression in clinical specimens of cancerous tissues and an association of ABRACL expression with proliferation and tumorigenic growth of colorectal cancer cells." (PMID 33670794, 2021).
gastric cancer (1 paper, 2021). A primary or metastatic malignant neoplasm involving the stomach. "In addition, ABRACL was detected to be upregulated in gastric cancer tissue compared to that in normal gastric tissue, which is associated with poor prognosis." (PMID 33728339, 2021).
cancer (6 papers, 2021 to 2023). A tumor composed of atypical neoplastic, often pleomorphic cells that invade other tissues. "Previously, it has been reported that ABRACL was highly expressed in a variety of cancers and was associated with poor patient prognosis." (PMID 35341461, 2022). "In addition, human ABRACL has been implicated in cancer cell migration, probably by modulating actin dynamics." (PMID 37759737, 2023). "Given that ABRACL and Dictyostelium Costars share remarkable sequence similarity and that ABRACL can rescue the migration defect of Costars-deficient Dictyostelium cells, we set out to test the role of ABRACL in cancer cell migration." (PMID 33670794, 2021). "However, our bioinformatics analysis suggests the upregulation of ABRACL as a common molecular alteration associated with cancer pathogenesis, as it is observed in various types of cancer." (PMID 33670794, 2021). "Together, results suggest that ABRACL modulates actin dynamics through its interaction with cofilin and thereby regulates cancer cell migration and participates in cancer pathogenesis." (PMID 33670794, 2021). "Taken together, these data suggest that ABRACL plays an important role in maintaining the tumorigenic potential of cancer cells." (PMID 33670794, 2021). "The low-migration phenotype of Dictyostelium cells with a knockout allele of the gene encoding the ABRACL ortholog Costars was recapitulated in human cancer cells depleted of ABRACL expression." (PMID 33670794, 2021). "It was suggested that miR-145-5p affected the physiological activities of cancer cells by regulating the expression of ABRACL." (PMID 33728339, 2021). "Our previous work has demonstrated that the depletion of the Dictyostelium Costars increases the cellular F-actin content, while in this study, we found that the suppression of ABRACL expression lowered the F/G-actin ratio in cancer cells." (PMID 33670794, 2021). "Here we report the role of ABRACL, a human homolog of the Dictyostelium actin regulator Costars, in migration and tumorigenic growth of cancer cells." (PMID 33670794, 2021). "In conclusion, this study demonstrates that the human Costars family protein ABRACL has the conserved function in regulating actin and cell migration and also highlights ABRACL as a molecular player in cancer pathogenesis." (PMID 33670794, 2021). "Actin-binding Rho activating C-terminal like (ABRACL) was highly expressed in several cancers." (PMID 35341461, 2022). "In cancer cells, downregulation of ABRACL suppresses proliferation, invasion, and migration." (PMID 36142365, 2022). "This evidence suggests that, as a regulator of actin, ABRACL may also be involved in regulating the malignant biological behaviors of cancer cells." (PMID 35341461, 2022). "In this study, we investigated the role of ABRACL in cancer cell migration." (PMID 33670794, 2021). "As cell migration is deemed pivotal in cancer pathogenesis, and because our findings suggested that ABRACL may regulate cell motility through modulating actin dynamics, we were prompted to investigate the expression of ABRACL in clinical specimens." (PMID 33670794, 2021).
ABRACL also shares sentences with these, for which no sentence is quoted: tumor (2 papers); Esophageal Carcinoma (1); psychiatric disorder (1).